CTLA4 (cytotoxic T-lymphocyte associated protein 4)
Diseases named in the same sentence as CTLA4 in open-access papers (continued):
Sharing a sentence is not in itself a finding about the gene and the disease.
tumor (continued). "In their study, they noted that fractionated local radiotherapy to one palpable tumor synergized with CTLA-4 blockade to induce antitumor T cell immunity and inhibit the growth of a second palpable tumor outside the radiation field." (PMID 22973551, 2012). "While CD4 effector infiltration and proliferation were only increased by CTLA-4 blockade, α4-1BB did increase inflammatory cytokine production from these cells both in the periphery and within the tumor itself." (PMID 21559358, 2011). "In contrast to the CD8 compartment, only CTLA-4 blockade appeared capable of driving CD4+ effector T-cell proliferation within the tumor." (PMID 21559358, 2011). "CD4 effector to Treg ratios in the tumor were also elevated in combination therapy, largely due to the effects of CTLA-4 blockade in promoting increased CD4 infiltration." (PMID 21559358, 2011). "The inhibitory activity of IL13, IL1b, PTGS2, NOS2, and CTLA4 on the immune response would enhance tumor growth." (PMID 22013484, 2011). "In line with the other examined compartments CD4+CD25highFOXP3+CTLA-4+ Tregs were also increased in the tumor draining mesenteric lymph nodes (TDLNs)." (PMID 24212779, 2011). "At the same time, levels of pro-inflammatory cytokines and chemokines, which potentially can support anti-tumor T-cell responses, were lower in tumors of mice that received anti-CTLA4-HSC therapy." (PMID 21779410, 2011). "Blockade of CTLA-4 signalling is possible via the administration of blocking antibodies, and this phenomenon has been exploited for the purposes of tumor immunotherapy." (PMID 21935390, 2011). "In the TC-1 model, so far, injection of anti-CTLA4 or expression from TC-1 cells significantly delayed tumor growth." (PMID 21779410, 2011). "Similar approaches were tested for tumor vaccines using fusion of CTLA-4 or CD28 and tumor antigens to enhance specific immunity to tumor antigens." (PMID 21799884, 2011). "In contrast to the study in the MMC model, anti-CTLA4 expression from TC-1 cells resulted in a significant delay in tumor growth." (PMID 21779410, 2011). "Here, α4-1BB dampened Treg proliferation, reduced the Treg fraction of TIL, counteracted αCTLA-4's expansion of absolute Treg numbers in the tumor, and decreased CTLA-4 and PD-1 expression by Tregs." (PMID 21559358, 2011). "Another member of the B7-CD28 family, PD-1 involves a distinct inhibitory pathway to inhibition of T cells in the tumor microenvironment and represents a potential target for therapy alone or in combination with CTLA-4 blockade." (PMID 21281484, 2011). "Tolerance against TAA has to be considered in tumor models that are used to delineate the anti-tumor mechanisms of anti-CTLA4 antibodies." (PMID 21779410, 2011). "In a mouse model, blockade of the PD-1 pathway was shown to synergize with CTLA-4 blockade in reducing tumor volume and improving overall survival." (PMID 21281484, 2011). "Initial studies in mouse models using transplantable colon carcinoma demonstrated that anti-CTLA-4 blockade led to rejection of the tumor following a brief period of tumor growth." (PMID 21281484, 2011). "While preclinical studies in mouse tumor models have shown anti-tumor efficacy of anti-CTLA4 injection or expression, anti-CTLA4 treatment in patients with advanced cancers had disappointing therapeutic benefit." (PMID 21779410, 2011). "4-1BB activation elicited strong infiltration of CD8+ T-cells into the tumor and drove the proliferation of these cells, while CTLA-4 blockade did the same for CD4+ effector T-cells." (PMID 21559358, 2011). "Among them, proteins of the B7 family play important roles in the immunoevasion of tumor cells and can suppress T-cell-mediated immunity by binding to the inhibitory receptor CTLA-4, e.g. B7.1 (or CD80) and B7.2 (or CD86)." (PMID 21884581, 2011). "In this study, we show that the presence of tumor-infiltrating CD4+CD25+ T cells are typical Tregs based on their CD4+CD25+FoxP3highCD45RO+CTLA-4+ phenotype and suppressive functions." (PMID 21935436, 2011).
tumor (continued). "In mice that received LV-aCTLA4 transduced HSCs, tumor anti-CTLA4 mRNA levels were 36-fold (+/−5) higher in Dox-treated mice compared to mice that received drinking water without Dox." (PMID 21779410, 2011). "Blockade of CTLA-4 in this context was shown to enhance anti-tumor immunity in humans primarily through T helper cell expansion/proliferation." (PMID 21935390, 2011). "When gene expression was analyzed with respect to tumor sizes, both immunosuppressive (CTLA4) and immune stimulatory (IFNγ and TNFα) genes were increased with increasing tumor size." (PMID 22013484, 2011). "We therefore assessed an approach that would allow in vivo delivery of the anti-CTLA4 gene to the tumor." (PMID 21779410, 2011). "James Allison, who discovered CTLA-4, recently wrote: Understanding the precise mechanism of CTLA-4 activity in vivo, and by extension, the mechanism of anti-tumor immune activity mediated by CTLA-4 blockade, is an area of active investigation." (PMID 24212939, 2011). "By day 7, IFNγ, CSF2, CXCL10, GZMB, PTGS2, TNFα, CD80, CCL22, IL12a, IL13, IL1b, IL6, NOS2, and CTLA4 were significantly upregulated in the tumor-bearing mice bladders and AGTR2 and GATA3 were downregulated." (PMID 22013484, 2011). "Both CTLA-4 blockade and 4-1BB stimulation resulted in higher CD8+ T-cell proliferation within the tumor as measured by expression of the cell cycle associated protein Ki-67." (PMID 21559358, 2011). "Both 4-1BB activation and CTLA-4 blockade decreased CTLA-4 and PD-1 expression by Tregs in the tumor." (PMID 21559358, 2011). "Because viral gene transfer to epithelial tumors is inefficient, we employed a new stem cell based approach to deliver the anti-CTLA4 gene to the tumor." (PMID 21779410, 2011). "Antibody blockade of CTLA-4 removes these suppressive signals and allows tumor-specific T-cells which would otherwise be anergized to expand and continue to perform effector functions." (PMID 21559358, 2011). "CD4+Foxp3GFP+ cells in the tumor draining lymph nodes and tumors express higher levels of CTLA-4 and GITR than activated Foxp3GFP- cells." (PMID 21049016, 2010). "In the setting of cancer, several studies have found enhanced numbers of tumor-specific polyfunctional T cells in patients responding favorably to various forms of immunotherapy, including adoptive T-cell therapy, α-CTLA-4 antibody therapy, and tumor vaccines." (PMID 21203522, 2010). "CTLA-4 blockade is another potential strategy to be combined with adoptive cell transfer for effective host responses against tumor." (PMID 19175928, 2009). "Administration of antagonistic anti-CTLA-4 mAbs demonstrated antitumor effects in different murine tumor models including colon, prostate and renal carcinomas, as well as fibrosarcoma and lymphoma." (PMID 19272130, 2009). "DTA-1, an antibody for GITR, can abrogate Treg suppression while not depleting Treg, can reverse Teff/Treg ratio and increase CD4 T cell infiltration into tumors, and can synergize with CTLA-4 blockade to enhance anti-tumor immunity." (PMID 19175928, 2009). "For example, B16-BL6 was used in the original description of therapeutic vaccination with irradiated GM-CSF-transfected tumor cells and blocking antibody to CTLA-4." (PMID 19812695, 2009). "Activation of vasculature in tumors, extravasation and proliferation of T cells, and increased ratios of Teff/Treg and IFN-γ/IL-10 were discovered to be the mechanisms of anti-tumor effects of CTLA-4 blockade in mouse models." (PMID 19175928, 2009). "Anti-CTLA-4 administered alone can be effective against transplanted and spontaneous tumour models in mice." (PMID 19384299, 2009). "One of the most promising results was obtained from clinical trials combining antibodies against CTLA-4 with other immunotherapies such as application of GM-CSF-transduced tumor-cell vaccines." (PMID 19272130, 2009). "Other animal studies showed the potency of anti-CTLA-4 antibodies against poorly immunogenic tumours when used with other modes of treatment." (PMID 19384299, 2009).
tumor (continued). "CTLA-4 blockade leads to enhancement of the immune response, rejection of tumors, or even cures mice of tumors when used in combination with tumor vaccines." (PMID 17825114, 2007). "CTLA-4 blockade is therefore a potent strategy for the amplification of immune responses against weak antigens, e.g. tumour antigens, during vaccination and is currently being tested in clinical cancer trials." (PMID 17662155, 2007). "Allison presented evidence that blocking CTLA-4 signaling can dramatically improve T-cell mediated killing of tumor cells, leading to development of effective clinical strategies." (PMID 17049090, 2006). "We previously showed that immune modulation by blockade of CTLA-4 signalling enhances anti-tumour immunity after radiofrequency ablation." (PMID 16953240, 2006). "Combined treatment with MK-8722 and anti-CTLA-4 shows a synergistic tumor-suppressive effect." (PMID 41486149, 2026). "Moreover, it has been verified that IPS value, ranged from 0 to 10, was positively bound up with tumor immunogenicity and considered to be a new predictor of immunotherapy response to anti-CTLA-4 and anti-PD-1." (PMID 41551463, 2026). "Immune checkpoint inhibitors (ICIs) targeting PD-1/PD-L1 and CTLA-4 can produce durable remissions in multiple solid tumors, yet primary and acquired resistance remain frequent, often sustained by an immunosuppressive tumor microenvironment (TME)." (PMID 41654940, 2026). "Combining ES-072 with anti-CTLA-4 significantly suppresses tumor growth in mouse breast allografts." (PMID 41486149, 2026). "Therefore, high CTLA4 expression signals an immunologically active (‘hot’) tumor microenvironment, in which the survival benefit by the cytotoxic T cells outweighs the checkpoint’s suppressive effects." (PMID 41596281, 2026). "Combining curcumin with anti-CTLA-4 leads to marked tumor suppression." (PMID 41486149, 2026). "Since curcumin blocks the PD-L1/PD-1 pathway, combination therapy with curcumin and anti-CTLA4 may enhance tumor immunity." (PMID 41522360, 2026). "Additionally, mice treated with [211At]1 (675 kBq) and anti-CTLA-4 antibody showed superior tumor growth inhibition compared with mice treated with only [211At]1 (675 kBq)." (PMID 40768094, 2026). "Immunogenomic analyses linked high DCAF7 to CD4+ T‐cell enrichment, broad upregulation of checkpoint genes (PD‐1/PD‐L1, CTLA‐4, TIGIT), and increased tumour mutational burden, microsatellite instability and neoantigen load, suggesting an immune‐evasive phenotype." (PMID 41472554, 2026). "In tumor cells, elevated expression of β-catenin can prevent spontaneous T-cell activation and infiltration into the tumor microenvironment, thereby contributing to resistance against immune checkpoint inhibitors, such as PD-1 and CTLA4 therapies." (PMID 41535254, 2026). "Previous studies revealed that CTLA-4 expression was detected via immunohistochemistry in tumor-infiltrating lymphocytes, and higher staining scores or frequencies of positive cells were associated with poor clinical outcomes in canine mammary gland and melanocytic tumors." (PMID 40463388, 2025). "A high CTLA-4 epithelial score was linked to positive lymph nodes (LNs), the presence of infiltrative tumor border configuration (TBC), and the absence of peritumoral lymphocytes." (PMID 40149674, 2025). "Immune checkpoint blockade therapies such as PD-1 antibodies such as Pembrolizumab and Nivolumab, anti-PD-L1 antibodies such as Avelumab, Durvalumab, and Atezolizumab, and humanized CTLA-4 antibodies such as Tremelimumab and Ipilimumab have exhibited powerful and lasting anti-tumor action." (PMID 39994019, 2025). "For example, SCFAs can limit the anti-tumor activity of anti-CTLA-4 immunotherapy." (PMID 41278473, 2025). "Thus, CTLA-4 blockade exerts a dual effect—enhancing anti-tumor immune responses while concurrently promoting immunosuppressive mechanisms." (PMID 41045934, 2025).
tumor (continued). "Through the “synaptic hijacking” mechanism of CTLA4, Tregs precisely weaken the antitumor function of effector T cells from both antigen presentation and T cell signal regulation aspects, providing strong support for tumor immune escape." (PMID 41415289, 2025). "Overall, the results of this study demonstrated that LTX-315 plus anti-CTLA-4 antibody could synergistically improve the immunosuppressive microenvironment of residual tumors and induce a strong anti-tumor immunity after iRFA of HCC." (PMID 40222972, 2025). "Tumor-associated M2 macrophages and CD4+ CD25+FoxP3+ regulatory T-cells (Tregs) suppress anti-tumor immune responses through secretion of immunosuppressive cytokines IL-10 and TGFβ, and presentation of CTLA4 on T cells and PD-L1 on macrophages." (PMID 40831543, 2025). "Consequently, immunotherapies targeting CTLA-4 have been formulated and have demonstrated significant potential in augmenting anti-tumor immune responses." (PMID 41233805, 2025). "Additionally, studies demonstrate that CTLA-4+ cancer cells, mainly from BC, suppress the maturation and function of DCs, critical orchestrators of anti-tumor immunity." (PMID 40281554, 2025). "Our findings indicate that CTLA-4 expression in HNSCC plays an important role in tumor progression toward higher-grade neoplasia and may be linked to tumor biological behavior." (PMID 40861696, 2025). "In our study, we found that the HP infection score in the tumor group was notably higher than that in the normal group and screened five key prognostic genes (CTLA4, CPVL, EMB, CXCR4, and FAM241A) from the HP infection–related DEGs in STAD to establish a riskscore model." (PMID 39886652, 2025). "Moreover, ICAM-1 is an effective target for tumor inhibition following CTLA-4 abrogation or CAR-T cells treatment." (PMID 40071851, 2025). "Antibodies to CTLA-4 have made a successful transition from bench to bedside for the treatment of several cancers, but there is uncertainty about how they achieve their anti-tumour effects." (PMID 40265076, 2025). "Consequently, the use of CTLA-4 blockade in ocular diseases is anticipated to enhance anti-tumor immunity by promoting T-cell activation and diminishing the inhibitory effects of Tregs." (PMID 41268982, 2025). "The results revealed that B68 significantly suppressed tumor growth without affecting body weight, which was better than the effect of anti‐PD‐1 and anti‐CTLA4, suggesting that B68 suppresses tumor growth through senescence in addition to its immune checkpoints." (PMID 39721027, 2025). "For instance, in breast cancer models, PLGA nanoparticles co-encapsulating paclitaxel and anti-CTLA-4 antibodies demonstrated a 50% greater tumor regression rate than either agent alone, indicating a powerful synergy between cytotoxic and immunomodulatory mechanisms." (PMID 40872479, 2025). "Tumor-infiltrating cytotoxic T cells can be inhibited by the co-inhibitory signal of CTLA-4." (PMID 40943370, 2025). "CTLA-4 and PD-1 provide key physiological immune regulatory mechanisms, and extensive experimental data have shown that blocking these checkpoints with antibodies can enhance anti-tumor immune responses in animal models." (PMID 40066456, 2025). "Firstly, the localized and sustained release of checkpoint inhibitors (e.g., anti-PD-1, anti-PD-L1, anti-CTLA-4 antibodies) from the hydrogel depot maintains high therapeutic concentrations within the tumor microenvironment (TME) while minimizing systemic exposure and associated toxicities." (PMID 40690143, 2025). "Finally, research has shown that the gut microbiota can alter the tumor microenvironment; for instance, Bacteroides fragilis enhances the efficacy of anti-CTLA-4 therapy by remodeling the tumor microenvironment through immunomodulatory mechanisms." (PMID 40806182, 2025).
tumor (continued). "In the R1LWT SQ murine HCC model, intratumoral administration of MMR combined with antibodies that block PD-1 and CTLA-4 (i.e., triple-combination therapy) suppressed tumor growth and reprogrammed the TME by enhancing CTL infiltration, reducing PD-1+ exhausted T cells, and polarizing TAMs." (PMID 41142777, 2025). "Distribution of quantitative parameters relative to mitotic count, Ki67 index, nuclear atypia and counts of CD3+/CD20+ positive tumour infiltrating lymphocytes with respect to PD‐L1, PD‐1 and CTLA‐4 ACD RNAscope semi‐quantitative scores in neoplastic cells (Wilcoxon's rank‐sum test)." (PMID 39789732, 2025). "Currently, there are at least four types of immunotherapy strategies: immune checkpoint inhibitors (ICIs), such as programmed cell death protein 1 (PD-1) and Cytotoxic T-Lymphocyte Antigen 4 (CTLA-4), chimeric antigen receptor T cell therapy, tumour vaccines, and lastly, peripatetic immunotherapy." (PMID 39941847, 2025). "It is plausible that CTLA4+ tumor cells may contribute to immune evasion by directly suppressing immune effector functions, thereby promoting disease progression and resistance to therapy." (PMID 41008794, 2025). "Next, we sought to determine whether B68 could synergize with anti‐CTLA4 to inhibit tumor growth in vivo by using an MC38 mouse cancer model." (PMID 39721027, 2025). "Furthermore, there is significant potential in combining NF-κB inhibitors with immune checkpoint inhibitors, such as anti-PD-1 and anti-CTLA-4 therapies, for enhancing the anti-tumor immune response." (PMID 39949765, 2025). "ICIs, such as antibodies targeting programmed cell death protein 1 (PD-1) or its ligand PD-L1, and cytotoxic T-lymphocyte-associated protein 4 (CTLA-4), function by releasing the brakes on the host immune system, enabling T cells to recognize and attack tumor cells." (PMID 41221298, 2025). "However, the combination of two SNPs, namely rs1129055 of CD86 gene and rs231775 of the CTLA4 gene caught our attention because CD86 and CTLA4 engage in a receptor-ligand interaction that inhibit anti-tumor immune response." (PMID 41469691, 2025). "In response to these signals, tumor-resident Tregs undergo transcriptional and epigenetic remodeling, often acquiring a tissue-adapted phenotype marked by high expression of immune checkpoints (e.g., CTLA-4, TIGIT, PD-1) and enhanced suppressive capacity." (PMID 40660400, 2025). "Similarly, combining OX40 agonists with CTLA-4 inhibitors has shown superior anti-tumor efficacy compared to either agent alone, underscoring the synergistic potential of these therapies." (PMID 40165967, 2025). "For instance, clinical trials exploring the combination of CAR-T cells with immune checkpoint inhibitors, such as anti-PD-1 or anti-CTLA-4 antibodies, could enhance therapeutic efficacy by overcoming the immunosuppressive tumor microenvironment." (PMID 40312353, 2025). "For instance, the expression of programmed cell death protein 1 (PD-1/CD279) and check-point blockade of cytotoxic T lymphocyte antigen 4 (CTLA-4/CD152) may differ among tumor-infiltrating lymphocytes compared to circulating T cells." (PMID 40643518, 2025). "Systematic integration of additional variables, such as peripheral immune-cell ratios, tumor-infiltrating lymphocyte composition, and checkpoint-molecule expression (e.g., PD-1, PD-L1, and CTLA-4), would markedly enhance dataset granularity and biological interpretability." (PMID 41346390, 2025). "Notably, several of these checkpoints (e.g., PDCD1, LAG3, TIGIT and CTLA4) collectively impair T cell function through distinct mechanisms, driving immune evasion and tumor progression." (PMID 41562077, 2025). "Therefore, blocking PD-1/PD-L1 and CTLA-4 with ICIs to restore the body’s anti-tumor immune function is an effective measure for treating ES-SCLC." (PMID 41256848, 2025).